RECK (reversion inducing cysteine rich protein with kazal motifs)
Diseases named in the same sentence as RECK in open-access papers (continued):
Sharing a sentence is not in itself a finding about the gene and the disease.
tumor (continued). "The membrane-anchored MMP-regulator reversion-inducing-cysteine-rich protein with kazal motifs (RECK) regulates tumor invasiveness and, via direct interaction, negatively regulates MMP-9 and inhibits tumor invasion and metastasis." (PMID 19226458, 2009). "Pro-metastatic genes (VEGF-A, MMP-9 and CXCR4) are up-regulated, and the tumor inhibitory gene (RECK) is down-regulated in xenograft tumors developing in presence of PICP." (PMID 19226458, 2009). "Previous studies have revealed that RECK is able to inhibit tumour angiogenesis, invasion, and metastasis." (PMID 18665171, 2008). "RECK is a novel tumour suppressor gene that negatively regulates matrix metalloproteinases (MMPs) and inhibits tumour invasion, angiogenesis and metastasis." (PMID 18665171, 2008). "RECK, a novel metalloprotease inhibitor, is tentatively thought to limit tumour progression by inhibition of MMPs-2, -9 and -14 (each of which affects angiogenesis)." (PMID 15928670, 2005). "The expression of miR-21 is highly upregulated in tumor and non-tumor tissues, and it has been linked to low-level expression of RECK." (PMID 38612895, 2024). "Our experimental data suggest that downregulation of RECK by miR-21 may be selectively regulated in different types of tumor cells." (PMID 38612895, 2024). "Notably, the knockdown of miR-21 inhibited cell invasion by increasing RECK expression and decreased tumor growth in a xenograft model." (PMID 38612895, 2024). "Reversion-inducing cysteine-rich protein with kazal motifs (RECK) is a membrane-anchored protein that regulates matrix metalloproteinases (MMPs), which are involved in the invasion and metastasis of a variety of tumor cells and patient prognosis." (PMID 38686051, 2024). "Induced expression of RECK results in suppression of tumor angiogenesis, invasion, and metastasis." (PMID 38612895, 2024). "RECK overexpression appears to delay tumor growth and increase overall survival in vivo." (PMID 38612895, 2024). "Indeed, forced expression of RECK in tumor cells results in a decreased incidence of malignancies in animal models." (PMID 38139236, 2023). "Subsequently, RECK was screened as a tumor-related candidate gene using multiple bioinformatics strategies with the criterion of P < 0.05, including correlation analysis for clinical characteristic relevance, survival analysis, and receiver operating characteristic curve (ROC) analysis." (PMID 37904179, 2023). "The RECK gene has been reported to encode a membrane-anchored glycoprotein that can negatively regulate MMP-2 and MMP-9 activities and is strongly associated with tumor angiogenesis and metastasis in various human cancers." (PMID 36895489, 2023). "Furthermore, we demonstrated that the effect of BAP31 expression on angiogenesis in the tumor microenvironment by the BAP31/miR-181a-5p/RECK axis." (PMID 36895489, 2023). "Furthermore, the “Gene” module analysis revealed that the mRNA RECK level was remarkably relevant to tumor purity, B cells, CD4+ T cells, dendritic cells, macrophages, CD8+ T cells and neutrophils." (PMID 37255541, 2023). "Moreover, RECK exerted its tumor-suppressive effects by the inactivation of ERK/MAPK signaling in GC cells." (PMID 37904179, 2023). "Because angiogenesis and immunosuppression have been reported as connected processes that can occur in parallel, the functional inhibition of MMPs by RECK can suppress tumor growth not only through the reduction of angiogenesis but also through immune-related mechanisms." (PMID 38139236, 2023). "Furthermore, unpaired and paired difference analyses illustrated that RECK was downregulated in the tumor samples." (PMID 37904179, 2023). "Besides, EZH2 activity resulting from posttranslational phosphorylation at the serine-21 site is responsible for the increased enrichment of H3K27me3 at the RECK promoter region, which is related to tumor metastasis and angiogenesis." (PMID 37803297, 2023).
tumor (continued). "Elevated RECK expression implies enhanced immune response, which may render the individual more receptive to anti-tumor therapeutic interventions." (PMID 37904179, 2023). "RECK is a promising prognostic biomarker and may shape a high-tumor-immunity and low-metastasis microenvironment in patients with GC." (PMID 37904179, 2023). "In addition, the RECK gene is widely expressed in various human organs, but its expression is low or undetectable in many tumor-derived cell lines." (PMID 36895489, 2023). "It has been suggested that GAS5 modulates miR-21/RECK to increase the radiation sensitivity of tumor cells, and could therefore also serve as a target for improving the effect of radiotherapy." (PMID 35241975, 2022). "Our findings suggest that in addition to its function as a tumour suppressor, RECK may also play a role in infectious inflammation." (PMID 35892136, 2022). "Furthermore, in contrast to other cancer-derived cells, the tumour suppressor RECK is expressed at normal levels in BEAS-2B cells." (PMID 35892136, 2022). "We argue that RECK over expression leads to improved tumor cell adhesion, which may contribute, in part, to the observed reduced tumor volume in mice." (PMID 34066355, 2021). "It is unclear whether upregulation of RECK can lead to the recruitment of more immune cells into the tumor microenvironment and thus affect the prognosis of HCC." (PMID 34093791, 2021). "There are, at least, two not mutually exclusive possibilities to explain these results: (a) differences in the tumorigenic potential between control and RECK+ cells and, (b) differences in the tumor microenvironment of tumors established from control and RECK+ cells." (PMID 34066355, 2021). "If a therapeutic means of enhanceing RECK expression is developed, it may be valuable in improving prognosis and impeding tumor progression." (PMID 33987019, 2021). "It is, however, unclear whether RECK downregulation occurs prior to, concurrently, or following tumor metastasis." (PMID 34745017, 2021). "Besides, SW756 RECK+ tumor cells presented reduced viability when compared to control tumors, as indicated by detection of an increase in the sub-G1 population." (PMID 34066355, 2021). "RECK protein is involved in the suppression of tumor invasion, angiogenesis and metastasis." (PMID 34066355, 2021). "Histological analysis of tumor sections confirmed the presence of cells with monocyte/macrophage morphology in control tumors and detection of an increased number of cells with lymphocytic morphology in RECK+ tumors." (PMID 34066355, 2021). "RECK over expression (RECK+) delayed tumor growth and increased overall survival in vivo." (PMID 34066355, 2021). "The mechanisms underlying RECK downregulation in cancer are hypothesized to be multifactorial and tumor specific; however, the general mechanism appears to involve increased Sp1 binding to the RECK promoter, resulting in its reduced transcription." (PMID 34745017, 2021). "Hence, functional inhibition of MMPs by RECK can suppress tumor growth not only through the suppression of angiogenesis but also through immune-related mechanisms." (PMID 34093791, 2021). "RECK has been characterized as a tumor suppressor in different types of cancers including NSCLC." (PMID 32138716, 2020). "The gene RECK, which was replicated in this study, is known to be a tumor suppressor." (PMID 31338326, 2019). "RECK is an antimetastatic gene cloned from NIH3T3 cells encoding an extracellular protein and is a tumor suppressor through inhibiting MMPs thereby suppressing tumor invasion." (PMID 30733959, 2019). "This interaction may also affect the function of RECK itself, a tumor suppressor downregulated in a wide variety of cancers." (PMID 30287421, 2018). "RECK is considered to be a tumor and metastasis suppressor gene." (PMID 28134767, 2017).
tumor (continued). "In addition, we demonstrated that TMPRSS4 remarkably suppressed the expression of RECK, an inhibitor of angiogenesis, and drastically induced tumor angiogenesis and growth." (PMID 26190376, 2015). "RECK is a cysteine-rich, extracellular protein with a protease inhibitor-like domain that exerts a tumor suppressor function through negative regulation of MMPs and suppression of tumor invasion." (PMID 25537516, 2015). "Down-regulation of RECK has been shown to correlate with enhanced tumor invasion, angiogenesis, and metastasis, and Reck−/− mouse embryos die in utero at around E10.5 with prominent vascular defects including vessel dilation, hemorrhaging, and arrested development of the primary vascular plexus." (PMID 26051822, 2015). "Also, over-expression of RECK in several tumor-derived cell lines leads to suppression of the invasive and metastatic activity of these cells." (PMID 26431549, 2015). "The present findings also identify link between TMPRSS4 and RECK that may enhance our understanding of tumor angiogenesis and lead to the development of novel treatment strategies." (PMID 26190376, 2015). "Reversion-inducing cysteine-rich protein with Kazal motifs (RECK, a tumor suppressor) is down-regulated by the oncogenic signals and hypoxia, but the biological function of RECK in early tumorigenic hyperplastic phenotypes is largely unknown." (PMID 24376819, 2013). "The RECK gene is widely expressed in numerous normal tissues and non-neoplastic cell lines, but its expression is low or undetectable in oncogene-transformed fibroblasts or tumor-derived cell lines." (PMID 23833658, 2013). "RECK expression in normal and tumor cells appeared mainly granularly in the cytoplasm." (PMID 24131772, 2013). "Western blots also presented less amounts of RECK in the tumor tissue." (PMID 24131772, 2013). "Furthermore, the dose-dependent TGF-β1 functions on MMP-9 and RECK protein levels emphasize the multifaceted mechanism of this cytokine in the control of tumor invasion and metastatic capacities." (PMID 22260435, 2012). "We believe that miR-21 may be important in PCa progression through its regulation of RECK, a known regulator of tumor cell invasion." (PMID 22642976, 2012). "The RECK gene is extensively expressed in normal tissues, but down-regulated in tumor tissues." (PMID 23285167, 2012). "In conclusion, we believe that miR-21 may be important in PCa progression through its regulation of RECK, a known regulator of tumor cell invasion." (PMID 22642976, 2012). "Similarly, reversion-inducing cysteine rich protein with Kazal motifs (RECK) has been shown to reduce microvascular density, tumour invasion, and metastasis independently." (PMID 21559216, 2011). "RECK is frequently silenced in aggressive tumor cells by the HADC/SP1 binding in the RECK promoter." (PMID 21573219, 2011). "The second human hammerhead we subjected to further analysis, termed “RECK hammerhead”, resides in an intron of the gene for RECK (reversion-inducing cysteine-rich protein with Kazal motifs), a negative regulator of certain metalloproteinases involved in tumor suppression." (PMID 21573207, 2011). "RECK is an anti-oncogene inversely related to tumor invasion that is downregulated in many tumors." (PMID 19995435, 2009). "Also, RECK, recognized as a tumor suppressor in GC, is an important target of miR-21." (PMID 38081950, 2023). "The observed positive connection between the expression of RECK and the presence of CD8+ or CD4+ T cells implies that the GC patients exhibiting high levels of RECK may also exhibit a higher abundance of T cells in tumor environment, hence potentially indicating a more favorable prognosis." (PMID 37904179, 2023). "Thus, RECK promotes normal angiogenesis but suppresses tumor angiogenesis." (PMID 35149728, 2022). "Importantly, 30% of the animals injected with SW765 RECK+ cells exhibited tumor regression." (PMID 34066355, 2021).
tumor (continued). "In addition, positive RECK expression was associated with a lower incidence of vascular invasion and recurrence, a lower level of alpha fetoprotein (AFP) and microvessel density and a better tumor differentiation." (PMID 34093791, 2021). "Therefore, it is possible that RbAp46 could promote tumor metastasis by regulating transcriptional suppression on RECK gene through histone deacetylation activity." (PMID 25885317, 2015). "RECK may reduce tumor progression through functionally downregulating MMP-2 expression." (PMID 24765174, 2014). "The observation that hypoxia can cause RECK silencing in normal cells is important, as it could be a novel mechanism for reducing tumor suppressor expression under low oxygen tension-dependent stress, which characteristic of certain pathological conditions." (PMID 24376819, 2013). "The clinicopathological analysis revealed that the expression of RECK was not notably correlated with the age, gender, pathological classification or tumor stage of the patients, but that it was associated with extranodal lymphomatous involvement and prognosis in PTCL." (PMID 23833658, 2013). "Besides, a qRT-PCR study of RECK mRNA expression in various spontaneously developing canine tumors showed that expression levels were low in the majority of tumor tissues relative to normal tissues; however, in some neoplasias, RECK expression was higher than in the controls." (PMID 21726449, 2011). "Activation of the Ras pathway may reduce RECK expression and thereby increase tumour recurrence." (PMID 21385341, 2011). "Accumulating evidence indicates that RECK is down-regulated in various solid tumors and that the level of residual RECK expression in resected tumors often correlates with better prognosis, supporting the authenticity of RECK as a clinically relevant tumor suppressor." (PMID 20691046, 2010). "Moreover, these chemicals could up-regulate endogenous RECK protein in multiple human tumor cell lines as examined by immunoblot assay, with an exception of Pyt, which showed little effects on RECK expression in RZmet3 cells under these conditions." (PMID 21304177, 2010). "RECK may inhibit tumor invasion and metastasis by inhibiting the expression and activity of MMP-2." (PMID 19995435, 2009). "Thus, we argue that the proportion of stromal cells in the prostate tissue homogenates does not vary appreciably between benign and malignant tissues, and therefore the reduced expression of TIMP3, TIMP4 and RECK is most likely a functional consequence of tumour–stromal interactions." (PMID 15928670, 2005). "MiR-21 is an oncomiR whose overexpression promotes cancer progression by suppressing tumour-suppressor genes such as PTEN, PDCD4, and RECK, leading to increased proliferation, invasiveness, and resistance to apoptosis." (PMID 41375254, 2025). "Initially, the RECK gene was identified in v-Ki-Ras-transformed NIH 3T3 cells during the induction of a flat morphology, and it was thought to be a tumor suppressor gene that suppressed invasion." (PMID 38612895, 2024). "In HCC cells, miR-21 simultaneously regulates multiple programs that enhance tumor invasiveness by targeting PTEN, RECK, and PDCD4." (PMID 38139236, 2023). "It has been widely demonstrated that miR-21 can function as an oncogene, increasing tumor cell migration and invasion by directly targeting phosphatase and tensin homolog deleted from chromosome 10 (PTEN), RECK, and programmed cell death 4 (PDCD4)." (PMID 38139236, 2023). "Quantification of the immunoblot results demonstrates a statistically significant increase in RECK expression and reduction of MMP14 in rTIMP2 treated wt tumor-bearing mice compared with vehicle control (HBSS) treated wt tumor-bearing mice." (PMID 38234759, 2023). "Moreover, the cross-talk between tumor immunity and metastasis might be mediated by RECK." (PMID 37904179, 2023). "In addition, RECK might act as a link between tumor immunity and metastasis in GC in our analysis." (PMID 37904179, 2023).
tumor (continued). "The screened candidates, as the targets of miR-21 and miR-21*, included a large number of oncogenic proteins and tumour suppressors, such as Ras, GRHL3, CHL1, PDCD4, PTEN, RECK and HNRPK." (PMID 35421166, 2022). "Therefore, RECK may not only be a tumour suppressor but also play a role in inflammatory diseases." (PMID 35892136, 2022). "In contrast, several factors assigned to the suppression of tumor cell migration and/or invasion as well as angiogenesis, such as DLC1, RHOU, DACH1, and RECK, were significantly downregulated in the brain-seeking cell line in comparison with the native one." (PMID 35163822, 2022). "RECK over expression also correlated with higher protein levels of CD40/TNFRSF5 and lower levels of IL-8 protein in a SW756 derived tumor mice model." (PMID 34066355, 2021). "Besides a direct effect of RECK expression on cell oncogenic potential we hypothesized that over expression of this protein may induce changes in the microenvironment that may affect tumor establishment and progression in vivo." (PMID 34066355, 2021). "In order to address this issue, we analyzed the different cell populations present in the tumor microenvironment (TME) of control and RECK+ tumors." (PMID 34066355, 2021). "In the present study, we show that RECK expression reduces de tumorigenic potential of HPV-transformed cells in vivo and alters the profile of the tumor inflammatory infiltrate." (PMID 34066355, 2021). "miR-21 activates the EGFR/AKT signaling pathway via targeting tumor suppressor genes such as PTEN, PDCD4, APAF1, TPM1, TIMP3, RECK, FOXO1 and SPRY240." (PMID 32019988, 2020). "Overexpression of RECK reduced cell growth and invasion and abrogated the tumour‐promoting effect and MMP‐2/‐9 expression caused by miR‐15b, which was consistent with previous studies in cancer cells 20, 33, 38 indicating that miR‐15a might promote the tumorigenicity of PCa cells via targeting RECK." (PMID 29363862, 2018). "MiR-21 has been shown to affect cell proliferation, invasion, and the clinical outcome by downregulating the expression of tumor suppressors, such as PDCD4, TIMP3, RECK, and KRIT1." (PMID 28466015, 2017). "Most of targets for miR-21 have been identified as tumor suppressors, such as PDCD4 (Programmed cell death 4), PTEN, RECK, TP63 and FASLG." (PMID 29190966, 2017). "Since significant changes in transcript and protein expression of RECK and proangiogenic molecules were observed after 12 weeks of DMBA painting that correlated with tumour progression, we tested the chemotherapeutic efficacy of nimbolide at this time point." (PMID 28515436, 2017). "Focusing on the intro-1 region of the RECK CpG island, Hill and colleagues found a significant inverse correlation between its methylation (RIM) in tumor tissues and relapse-free survival of the patients." (PMID 27058625, 2016). "When RECK is down-regulated, the activity of MMP-9, a key enzyme involved in tumor invasion and metastasis, is increased." (PMID 25885317, 2015). "While miR-21 has been found to promote tumour proliferation and invasion in GC by negatively regulating important tumour suppressors such as PTEN, PDCD4, and RECK, and then confer GC cells with increased invasiveness and the ability to avoid anoikis." (PMID 24614175, 2014). "MiR-21 functions as an oncogenic microRNA by targeting multiple tumor suppressor genes including PTEN, PDCD4, BCL-2, TPM1, and RECK, and its participation has been reported in many human cancers." (PMID 25428915, 2014). "miR-21 simultaneously regulates multiple programs that enhance cell proliferation, apoptosis and tumor invasiveness by targeting PTEN, RECK and Bcl-2 in GSQCLC." (PMID 25084400, 2014). "Protein expression of the three target genes (FOXF2, RECK, MTSS1) was significantly higher in stable low miR-182-5p expressing xenograft tumor tissues." (PMID 23383207, 2013).